FASN (fatty acid synthase)
Diseases named in the same sentence as FASN in open-access papers (continued):
Sharing a sentence is not in itself a finding about the gene and the disease.
glioma (continued). "Inhibitors of additional metabolic enzymes in gliomas, such as glutaminase (GLS1) via CB-839, fatty acid synthase (FASN) via TVB-2640, isocitrate dehydrogenases (IDH) 1-2 via ivosidenib (AG-120) and vorasidenib (AG-881), and IDO-1 via indoximod (1-MT) and epacadostat (INCB024360)." (PMID 38292487, 2023). "Recent studies have shown that blocking key enzymes of fatty acid synthesis, such as fatty acid synthase (FASN) and ELOVL fatty acid elongase 2 (ELOVL2), suppressed glioma tumor growth in GBM xenograft models, further suggesting the importance of fatty acids for glioma growth and survival." (PMID 35513201, 2022). "Besides, when we analyzed relevant genes in the fatty acid synthesis pathway, we found that the FASN gene was overexpressed in CNS WHO grade 3 and 4 glioma samples in the range of 72 to 180-fold." (PMID 34573317, 2021). "Interestingly, the glioma exosomes contained ATP-citrate synthase (ACLY), which converts citric acid into acetyl coenzyme A, and fatty acid synthase (FASN), which synthesizes palmitate from acetyl coenzyme A in the presence of NADPH." (PMID 32708613, 2020). "The universal detectability of FASN in EVs suggests that FASN is a ubiquitous biomarker in glioma-derived EVs that is not restricted to any particular subtype." (PMID 32178271, 2020). "Here we identified fatty acid synthase (FASN), a key lipogenic enzyme which is highly expressed in malignant glioma cells, to be elevated in CD63- and CD81-positive EVs in glioma patient plasma samples, opening vital opportunities to sort brain tumor-specific EVs." (PMID 32178271, 2020). "Finally, fatty acid synthase (FASN) protein, a multifunctional enzyme that plays a central role in lipid synthesis, is particularly noteworthy in regard to glioma." (PMID 31936544, 2020). "Similarly, the enzyme fatty acid synthase (FASN) that mediates fatty acid synthesis has been reported to be highly active in the GSC lines G144 and G179, as well as in tumorspheres generated from glioma tissue samples surgically resected from patients after their diagnosis." (PMID 36497394, 2022). "Finally, the Krebs cycle and fatty acid synthesis pathways play central roles in cellular metabolism; we also found that the IDH1, SDHB, FASN, ACACA, and ELOV2 genes were overexpressed, resulting in significant disturbances in the cellular metabolism of gliomas." (PMID 34573317, 2021). "The expression of FASN and de novo lipogenesis are increased in glioma CSCs compared to non-CSCs." (PMID 30445800, 2018). "In addition, temozolomide decreased lipid synthesis related FASN without influencing CPT1a expression in the studied glioma cells." (PMID 30574020, 2018). "Both VPA and a selective FASN inhibitor TVB-2640 rewired the lipidome and promoted apoptosis in an IDH1 MT but not in an IDH1 WT glioma cell line." (PMID 39149696, 2024). "We show that both VPA and the selective FASN inhibitor TVB-2640 rewire the lipidome and promote apoptosis in an IDH1 MT but not an IDH1 WT glioma cell line." (PMID 39149696, 2024).
pancreatic cancer (50 papers, 2014 to 2025). "Collectively, ARID1A deficiency upregulates fatty acid metabolism to accelerate pancreatic tumourigenesis and FASN is a potential therapeutic target for ARID1A‐deficient pancreatic cancer." (PMID 40621620, 2025). "Increased lipid content has been observed in human pancreatic cancer and cell lines due to an increase in fatty acid synthase (FASN) expression which causes chemoresistance to gemcitabine, a widely used drug for the treatment of pancreatic cancer." (PMID 40655023, 2025). "In gemcitabine-resistant pancreatic cancer cells, a notably increase in FASN expression was closely associated with regulating ER stress, which resulted in apoptosis, and stemness." (PMID 35646898, 2022). "In this study, we identified a new therapeutic target FASN in ARID1A‐deficient pancreatic cancer." (PMID 40621620, 2025). "FASN is a potential therapeutic target for ARID1A‐deficient pancreatic cancer.Mutations in AT‐rich interactive domain‐containing protein 1A (ARID1A) gene are frequently found in pancreatic cancer." (PMID 40621620, 2025). "Our data suggested that FASN overexpression induced by ARID1A loss may promote ERK activity to stimulate the proliferation of pancreatic cancer cells." (PMID 40621620, 2025). "Similarly, an increase in FASN-mediated de novo lipogenesis is associated with gemcitabine resistance in pancreatic cancer." (PMID 41145471, 2025). "Increased FASN levels have been associated with resistance to gemcitabine in pancreatic cancer." (PMID 38425123, 2024). "Moreover, we identify FASN as a new therapeutic target in ARID1A‐deficient pancreatic cancer." (PMID 40621620, 2025). "To confirm the clinical relevance of our findings, we analysed ARID1A and FASN expression in a pancreatic cancer cohort from The Cancer Genome Atlas (TCGA) dataset and observed a negative correlation between ARID1A and FASN expression." (PMID 40621620, 2025). "Inhibition of FASN by siRNA also suppressed the growth of mouse (KAR#1 and KAR#2) and human (BxPC3) pancreatic cancer cells with ARID1A loss." (PMID 40621620, 2025). "We next used a pancreatic cancer patient cohort (n = 102) collected in our hospital to test the association between ARID1A and FASN with clinicopathological features of patients." (PMID 40621620, 2025). "An additional target of SREBP2 is fatty acid synthase which induces de novo synthesis of lipids resulting in gemcitabine resistance in pancreatic cancer." (PMID 38697978, 2024). "Upregulation of miR-195 prevents the proliferation and invasiveness through the fatty acid synthase/Wnt signaling pathway in pancreatic cancer." (PMID 38559560, 2024). "Other studies also demonstrated increased levels of fatty acid synthase (FASN) in gemcitabine-resistant pancreatic cancers, and FASN silencing downregulated the resistance." (PMID 38388563, 2024). "Downregulation of ACLY and FASN through AKT degradation together with CS direct inhibition resulted in an impressive response of gemcitabine in pancreatic cancer tumors." (PMID 38425123, 2024). "It has been reported that tyrosine phosphatase (Shp2) that contains an Src homology 2 (SH2) domain acts as a binding molecule linking ubiquitin E3 ligase COP1 to FASN, thereby regulating the ubiquitination and degradation of FASN in pancreatic cancer." (PMID 37190313, 2023). "FASN-mediated fatty acid synthesis promotes gemcitabine resistance in pancreatic cancer cells, whereas the FASN inhibitor, orlistat, reduces pancreatic cancer cell stemness." (PMID 37736551, 2023). "The results showed that miRNA-195 inhibits pancreatic cancer cell proliferation and invasion by regulating the FASN/Wnt signaling pathway." (PMID 36452489, 2022). "FASN plays a central role in lipid metabolism, so it has been extensively studied in pancreatic cancer, pancreatic ductal adenocarcinoma, NPC, and seven other tumors." (PMID 36452489, 2022).
pancreatic cancer (continued). "In breast and pancreatic cancers, fatty acid synthase (FASN) overexpression contributes to the resistance to a wide range of chemotherapeutics." (PMID 33918653, 2021). "Orlistat, a FASN inhibitor, induces ER stress and increases gemcitabine sensitivity in mouse models with orthotopic pancreatic cancer implantation." (PMID 32122374, 2020). "Overexpressed FASN in pancreatic cancer cells upregulates PKM2 expression, promoting glycolysis and gemcitabine resistance." (PMID 32122374, 2020). "In the same way, FASN has been shown to be upregulated in several cancers, including pancreatic cancer." (PMID 30913248, 2019). "Pancreatic cancer patients with high expression of FASN show a shorter overall survival than patients with low FASN expression, and FASN expression is correlated with poor response to gemcitabine therapy in pancreatic cancer cells." (PMID 29295482, 2017). "EGFR signaling is required for oncogenic KRAS-induced pancreatic tumorigenesis, and EGFR signaling activation also induces upregulation of FASN in pancreatic cancer cells in an ERK-dependent manner." (PMID 29295482, 2017). "Similarly, inhibition of fatty acid synthase (FASN) in BxPC3 human pancreatic cancer cells also decreased ERK activation." (PMID 40621620, 2025). "Moreover, FASN expression is highly expressed in ARID1A‐low tumours and is associated with worse survival in pancreatic cancer patients." (PMID 40621620, 2025). "However, patients with high FASN expression had significantly worse overall and disease‐free survival, underscoring FASN as a potential prognostic factor in pancreatic cancer." (PMID 40621620, 2025). "Additionally, FASN was reportedly upregulated in lipid-laden CAFs of pancreatic cancer in a mouse model." (PMID 41008850, 2025). "Moreover, upregulation of FASN in pancreatic cancer cells is found to facilitate gemcitabine resistance, supporting a possible role of FASN in acquired gemcitabine resistance." (PMID 38819674, 2024). "Overexpression of the FASN gene may be correlated with resistance to radiotherapy and gemcitabine in pancreatic cancer patients, and inhibition of FASN results in high cytotoxicity of this drug." (PMID 36408139, 2022). "A previous study showed that EPA suppressed ACC activity, which plays an important role in FA metabolism; thus, we next examined protein levels of ACC-1 and long-chain FA synthases (FAS and FASN) to determine their involvement in EPA-mediated inhibition of SUIT-2 pancreatic cancer cell viability." (PMID 33801246, 2021). "In addition, patients with pancreatic cancer expressing high levels of FASN display shorter overall survival period than patients with low FASN expression." (PMID 31832601, 2019). "Furthermore, high expression level of FASN resulted in a significantly poor prognosis of pancreatic cancer, and data from TCGA study suggest that FASN expression could be a marker of bad outcome in cervical and renal cancer." (PMID 33194695, 2020). "Each of the fatty acid synthase/Wnt, miR-148a/Wnt10b, Linc00261/miR-552-5p/FOXO3, and miR-454/FAM83A/TSPAN1 axes can be valuable biomarkers and potential therapeutic targets in pancreatic cancer." (PMID 38559560, 2024). "WB analysis revealed that vitamin C was able to downregulate FASN and ACLY expression in CRL‐2558 and Mia‐PaCa2 human pancreatic cancer cell lines." (PMID 38425123, 2024). "Timosaponin A3 can inhibit SREBP-1 and its targets, FASN and ACC, to reduce cell viability and increase cell cycle arrest and apoptosis of BxPC-3 cells and pancreatic cancer xenograft growth, which is independent in the Akt/GSK-3β pathway." (PMID 35912181, 2022). "A similar result showed that ACC suppression induced apoptosis in human pancreatic cancer cells treated with CPI‐613 or devimistat, a lipoic acid derivative, but FASN expression remained constant." (PMID 35243817, 2022).
pancreatic cancer (continued). "We also compared the expression of LXRβ and known target genes SREBF1, ABCA1, ABCG1, FASN, and SCD in pancreatic cancer tissue to normal pancreas tissue and found that transcript levels of LXRβ and its target genes are elevated in the tumor tissues." (PMID 33348693, 2020). "Fatty acid synthase (FASN, also known as onco-antigen 519), a key lipogenic enzyme involved in de novo lipid biosynthesis, is significantly upregulated in pancreatic tumor cells, which results in a significantly poor prognosis of patients." (PMID 29552330, 2018). "Elevated expression of FASN and ACC in cancer cells is related to markedly worse prognosis in many human cancers, including pancreatic cancer." (PMID 25895130, 2015). "In addition, inhibition of FASN by chemical inhibitors or siRNA knockdown attenuated ERK activation and proliferation in ARID1A‐defecient pancreatic cancer cells." (PMID 40621620, 2025). "To further examine the relationship among K-ras, PLA2G2A, and FASN, we first used the GEPIA dataset containing RNA-seq data of pancreatic cancer from TCGA and the corresponding normal tissues from GTEx to analyze the potential correlation among these molecules in clinical samples." (PMID 36233022, 2022). "Furthermore, FASN activity was found to be upregulated in gemcitabine-selected pancreatic cancer cell line G3K cells, although with no significant changes on the expression level of FASN." (PMID 38819674, 2024). "Our study showed that EPA treatment inhibited cell visibility and p-STAT3, HPS, and ACC-1, but not FASN expressions in KRAS-mutant SUIT-2 cells, suggesting that EPA treatment might reduce ACC-1-mediated de novo lipogenesis to downregulate the tumor growth and survival of pancreatic cancer cells." (PMID 33801246, 2021).
colon carcinoma (47 papers, 2007 to 2025). "Enhanced expression of fatty acid synthase (FASN) has been observed in a number of cancer cell types and expression levels have been shown to be correlated to colon cancer progression and survival." (PMID 37110166, 2023). "The inhibition of FASN has previously been shown to induce the increased expression of CDKN1A in human colon carcinoma cells." (PMID 36139650, 2022). "Specifically, de novo lipogenesis is a requirement of cancer cells and targeting fatty acid synthase (FASN) using the TVB-2640 FASN inhibitor is nowadays in phase I or II clinical trials for breast, lung and colon cancers." (PMID 33915900, 2021). "Increased FASN expression was found in colon cancer and UCEC (P < 0.001) relative to comparable tissues from the CPTAC dataset." (PMID 34879004, 2021). "Inhibition of HIF1α expression by Oroxylin A can decrease SREBP1 and FASN expression in the colon cancer cell line." (PMID 29588626, 2018). "Metformin is an activator of AMPK and an inhibitor of mTOR, and it decreases the expression of FASN and SREBP1c in colonic tumors from mice fed a high-energy diet." (PMID 26002551, 2015). "That result is consistent with the observation that carcinomas of the colon, prostate, ovary, breast, and endometrium all express high levels of fatty acid synthase." (PMID 17845722, 2007). "Furthermore, this acid has been shown to reduce cell proliferation, migration, and invasion by inhibiting FASN and inducing apoptotic pathways in colon cancer." (PMID 41516111, 2025). "Moreover, there are compelling links between FASN expression and worse oncologic outcomes across multiple tumor types, and a significant interaction with BMI has been noted for both prostate and colon cancer, highlighting FASN as a metabolic oncogene." (PMID 38112617, 2024). "Additionally, an increase in de novo fatty acid biogenesis is a metabolic attribute that equips tumours with proliferative and survival benefits, and therefore, FASN (fatty acid synthase) is overexpressed in many cancers, including colon cancer." (PMID 37117602, 2023). "Importantly, in the tumors of the CAC mouse model, a higher expression of FASN and Hakai was detected, further supporting the implication of both proteins in colon cancer." (PMID 36266428, 2022). "Here we show that by employing two drugs clinically tested in the 80s, which are inhibitors of glycolysis –lonidamine-22,23 and glutaminolysis –DON-24–26, plus the well-known inhibitor of FASN -orlistat-10,21, effective in vitro and in vivo effects against colon cancer cells are found." (PMID 33664364, 2021). "Cerulenin is a FASN inhibitor, known for inducing apoptosis and inhibiting tumour growth in preclinical studies, It demonstrated efficacy in colon cancer, leading to a marked decrease in liver metastasis with reduced pAkt levels in a mouse model of colon cancer." (PMID 38610991, 2024). "The enzyme fatty acid synthase (FAS) plays a pivotal role in de novo fatty acid synthesis, making it a promising target for combating colon cancer." (PMID 38474695, 2024).
colon carcinoma (continued). "While HCT116 cells expressed the highest protein level of fatty acid synthase (FASN), an important enzyme for colon carcinoma development, lower protein levels of FASN were expressed in SNU-C2A, SNU-C5, and SW480 cells." (PMID 34073059, 2021). "In addition to an effect on glycolytic metabolism, ARS inhibited HCT116 colon cancer cell proliferation by suppressing the fatty acid biosynthetic pathway, mainly downregulating three proteins: acyl-CoA synthetase 5, hydroxyacyl-coenzyme A dehydrogenase and fatty acid synthase." (PMID 34684095, 2021). "Interestingly, one study reported that, among non-obese patients with colon cancer, tumoral FASN overexpression is associated with better survival, while among moderately overweight or obese patients, FASN overexpression may predict a poorer outcome." (PMID 33194695, 2020). "Box plots showing log2 transformed and median normalized values for (a) FASN (b) HMGCR (c) MGLL expression levels in KCL22 (Leukemia), KG1 (Leukemia), KU812 (Leukemia), SW480 (Colon cancer), SW620 (Colon cancer) and A549 (Lung Cancer)." (PMID 31138183, 2019). "Using RNAi we have demonstrated that depletion of fatty-acid synthesis pathway enzymes SCD1, FASN, or ACC1 in HCT116 colon cancer cells results in cytotoxicity that is reversible by addition of exogenous fatty acids." (PMID 22457791, 2012). "BER has previously been demonstrated to decrease lipid accumulation in porcine oocytes, colon cancer cells, and mouse liver tissue by suppressing the expression of genes that drive lipid buildup, such as SCAP, SREBP-1, PPARG, SCD1, and FASN." (PMID 37237857, 2023). "For the top colon cancer MEGs, the consistent tumor suppressor genes included MAP2K4, MAPK10, RUNX3, WNK2 (the four genes were identified by the TSGene 2.0 database), BECN1, FASN, NAT1, and NR3C2." (PMID 33273919, 2020). "Moreover, the influences of OA on the levels of HIF1α, FASN and CPT1 in the high-fat diet group were more obvious than those in the normal diet group, suggesting that high activity of lipid metabolism made colon cancer cells more sensitive to OA." (PMID 28594405, 2017). "Similar to Efipladib (an inhibitor of fatty acid cleavage), Cerulenin (a fatty acid synthase inhibitor) decreased AKT phosphorylation at Ser473, enhanced antitumor activity of oxaliplatin in human colon cancer cells, and suppressed liver metastasis of colon cancer in mice." (PMID 25365190, 2014). "Our data are in line with recently observed upregulation of FASN and FADS2 in colon tumors, where particularly the overexpression of FASN was negatively associated with CRC patient survival." (PMID 34206240, 2021). "Increased expression of FASN, ACC, and ACLY, together with significantly increased levels of several types of FAs, thus confirms that de novo synthesis of FAs is upregulated directly in colon cancer epithelial cells, and not just in whole tumors." (PMID 34206240, 2021).